MYC (MYC proto-oncogene, bHLH transcription factor)
Diseases named in the same sentence as MYC in open-access papers (continued):
Sharing a sentence is not in itself a finding about the gene and the disease.
lymphoma (continued). "In patients with double expressing lymphomas, where co-expression of MYC with BCL2 on immunohistochemistry are detected without associated translocations identified on in-situ hybridization, CNS recurrence risks can be as high as nine percent as compared to two percent in non-expressors." (PMID 38173015, 2024). "High-grade B-cell lymphoma with MYC and BCL2 and/or BCL6–R (DHL/THL) are defined by their genetic background and were recognized as highly aggressive B-cell lymphomas that can occur de novo or as transformations from prior lymphomas, most often FL or DLBCL, nos." (PMID 37530792, 2024). "Moreover, our analysis of CRISPR-Cas9-based loss-of-function screens demonstrated potential relationship between HSP90 and MYC, which is specific to lymphoma and not observable at the pan-cancer level." (PMID 38326887, 2024). "Furthermore, DLBCL is an aggressive tumor in itself, and poor clinical outcome is increased by overexpression of MYC and BCL2 proteins (double-expressor lymphoma, DEL) and a post-germinal immunohistochemical subtype of DLBCL (non-germinal center B-cell (non-GCB)-DLBCL)." (PMID 38542040, 2024). "In addition, MYC protein expression varies considerably in DLBCL with MYC translocation, ranging from negative to 100% positivity in lymphoma cells." (PMID 38184753, 2024). "In a research model of lymphoma, the lack of the MYC oncogene dilutes the growth of tumors." (PMID 39281673, 2024). "Both in WHO-HAEM5 and the ICC, however, a fundamental change is that this entity comprises only cases with MYC and BCL2 rearrangements (DLBCL/HGBL-MYC/BCL2), with or without additional BCL6 breaks, so that aggressive lymphomas with dual rearrangements of MYC and BCL6 (without BCL2) are excluded." (PMID 37190213, 2023). "Although a prior study suggested that indirect inhibition of MYC degradation by targeting glycogen synthase kinase 3β (GSK-3β) can increase doxorubicin sensitivity, others have shown that translation inhibition in chemoresistant lymphomas restores sensitivity to doxorubicin." (PMID 37768948, 2023). "Our pre-leukaemic analysis and the immuno-phenotyping of the malignant Eμ-MYC lymphoma cells revealed that the absence of TFAP4 resulted in the accumulation of pre-B cells, indicating a block in B cell development as a possible cause of accelerated c-MYC-driven lymphomagenesis." (PMID 36894688, 2023). "Translocation status of MYC in our panel of ten lymphoma cell lines did not predict sensitivity." (PMID 36792656, 2023). "In addition to COO, chromosomal translocations of BCL6, BCL2, and c-MYC are common cytogenetic abnormalities in DLBCL, and GCB lymphomas harboring these genetic lesions are called “double hit” lymphoma (c-MYC plus BCL2 or BCL6) or triple hit lymphoma (c-MYC plus BCL2 plus BCL6), respectively." (PMID 37566004, 2023). "Of interest, these signatures identify not only aggressive lymphomas with this double hit status but also a significant number of lymphomas that do not harbor MYC and BCL2 rearrangements, although in some of them, retrospectively, cryptic rearrangements have been detected." (PMID 37190213, 2023). "The breakpoints showed a much wider range around the MYC locus during MYC-R, and the breakpoint clusters were not as distinct in MM as the clusters in lymphomas, which may explain the low detection rate of MYC-R in MM via FISH." (PMID 38067393, 2023).
lymphoma (continued). "If BCL-W is required to support the ongoing survival of lymphoma cells, it is possible that such compensatory changes could occur to allow MYC-driven lymphomagenesis in the absence of BCL-W." (PMID 37567974, 2023). "However, another study confirmed that in c-MYC-overexpressing malignant lymphoma cells, the gene expression of PRPS2 rather than PRPS1 is strongly regulated at the translational level to regulate purine synthesis." (PMID 36203561, 2022). "However, mouse models that accurately mimic aggressive lymphomas, such as double hit lymphoma (DHL), an aggressive subset (~10%) of diffuse large B cell lymphomas (DLBCLs) that express high levels of both c-MYC and BCL-2 due to chromosomal translocations, are lacking." (PMID 35961968, 2022). "As in murine lymphoma cells, the decrease of MYC was not due to transcriptional changes." (PMID 36068335, 2022). "Thus, the MYC activity score could be validated in the HOVON-84 cohort and showed a clear correlation with DE and ABC-type lymphomas." (PMID 35267654, 2022). "However, about half of the DLBCL from the identified the high risk group did not harbor gene rearrangements of MYC and BCL2, suggesting the existence of alternative genetic or epigenetic alterations causing a high-grade lymphoma phenotype." (PMID 35060000, 2022). "Furthermore, it is known that, in DLBCL, oncogenic MYC could induce choline metabolism by transcriptionally activating the key enzyme PCYT1A, resulting in impeded mitophagy-dependent necroptosis of the lymphoma cells." (PMID 36291856, 2022). "In this case study, the lymphoma cells exhibited high levels of BCL2A1 expression and it was suggested that BFL-1 could play a role in the survival of these cancer cells similar to the role played by BCL-2 in the more common MYC/BCL-2 double-hit lymphomas." (PMID 35900226, 2022). "The lymphoma type-specific protein landscape of splenic CD19 + B cells of SLE-prone mice was analyzed by western blot for the expression of BCL2, that together with c-MYC defines the class of “double expressor” lymphomas, and for IRF4, an additional marker belonging to the ABC-DLBCL signature." (PMID 36503430, 2022). "However, these prognostic indices do not capture lymphoma related molecular aberrations causing particularly aggressive high-risk disease, such as cell of origin, activated B-cell type DLBCL, MYC and/or BCL2 and/or BCL6 gene re-arranged or double expressor lymphomas." (PMID 35238275, 2022). "In this context, berberine effectively suppressed DLBCL cancer cells growth by inhibiting the MYC-driven downstream effector PCYT1A, and inducing mitophagy-dependent necroptosis, thus being eventually considered as a promising anticancer agent to treat MYC-overexpressing lymphomas." (PMID 33467668, 2021). "Although MYCN is more commonly deregulated in human solid tumors (especially for childhood onset), it has also been reported translocated in human lymphomas, mouse plasma cell tumors, and, importantly, expressed in the very few human BL cases apparently lacking MYC deregulation." (PMID 33816589, 2021). "BCL2, BCL6 and MYC translocations are not mutually exclusive and may occur together in the same patient, forming the double-hit and even triple-hit lymphomas." (PMID 33996608, 2021). "Differently from tumors with an immunohistochemical expression of MYC and BCL2 (double expressors), aggressive B-NHLs harboring MYC and BCL2 or MYC and BCL6 rearrangements—when identified with FISH—present an even more aggressive behavior, and are also referred to as double-hit lymphoma." (PMID 34943410, 2021). "According to the current WHO classification in these MYC-negative cases, stringent clinical, morphological and immunophenotypic criteria need to be used to rule out lymphomas that may simulate BL." (PMID 34572754, 2021). "We reasoned that the pre-tumor setting rather than the MYC-driven lymphoma setting may more faithfully reflect the role of IL-6 in the earliest steps of Eμ-myc tumorigenesis." (PMID 33651821, 2021).
lymphoma (continued). "Moreover, while BCL2 transgenic mice only develop tumors with a low frequency or after cooperation with other oncogenes (e.g., MYC), MCL1 transgenic mice were shown to develop lymphomas (predominantly FL and DLBCL) with high probability (>80%), although with a long latency (over 6 months)." (PMID 34576319, 2021). "Indeed, MYC and EZH2 act in concert to silence tumor suppressor miRs in aggressive lymphoma cells." (PMID 32549409, 2020). "Moreover, restored expression of full-length TRIB3 or the KDC domain of TRIB3 reversed the repressed proliferation of lymphoma cells induced by TRIB3 deletion, indicating that the KDC domain of TRIB3 interacts with MYC, which stabilizes MYC and enhances lymphoma cell proliferation." (PMID 33298911, 2020). "It has been shown that antioxidants such as N-acetylcycteine and vitamin C inhibit MYC-driven lymphoma xenograft growth in vivo by targeting HIF1, which can be rescued by the expression of oxygen-independent HIF1 mutant, supporting a key role of HIF1 in MYC-driven tumors." (PMID 33251216, 2020). "To more accurately assess the impact of MYC amp on OS, we excluded 13 cases that would be expected to have poor outcomes: MYC amp at lymphoma relapse (N = 5), non-DLBCL morphology (N = 5; 3 HGBCL; 2 plasmablastic lymphomas) and transformation from CLL or FL with prior anthracycline use (N = 3)." (PMID 31932576, 2020). "Lymphomas that carry MYC and either a BCL2 or a BCL6 translocation (a double-hit lymphoma, DHL) or all three rearrangements (a triple-hit lymphoma, THL) are included in the current WHO classification as a new entity termed “High-grade B cell lymphomas with MYC and BCL2 and BCL6 rearrangements”." (PMID 32102485, 2020). "However, the majority of mice harboring MYC developed lymphomas in their axillary and inguinal lymph nodes and spleen, which was somewhat (not significantly) delayed by the genetic ablation of both copies of the Il6ra." (PMID 31515941, 2019). "Although our study has focused on the treatment of DHLs with genomic translocation of MYC and BCL2, the concept of simultaneously targeting multi-driver oncogenes may be extended to other DHLs or triple-hit lymphomas (THLs) with genomic abnormalities in BCL6 oncogene." (PMID 31752970, 2019). "In the absence of the MYC transgene, none of the mice of this line developed lymphomas." (PMID 31515941, 2019). "According to this description, we can hypothesize that MYC overexpression observed in lymphomas has a predominantly quantitative rather than qualitative effects on the related miRNA circuitry and other cellular process." (PMID 30038718, 2018). "However, the onset of disease was not significantly different between Eμ‐MYC/Vav‐BFL1 mice that harboured CD19−B220+CD4+ progenitor cell lymphomas in their thymus and those that did not (Kaplan–Meier plot)." (PMID 29498802, 2018). "Together, our findings underline the major impact of elevated BFL1 on tumour development, an effect that might not be confined to MYC‐induced lymphomas." (PMID 29498802, 2018). "In the same cell contexts, we also tested Tigecycline, another tetracycline that was recently shown to curb proliferation of MYC-overexpressing lymphoma and osteosarcoma cells, but we did not achieve the anti-proliferative effects of doxycycline (data not shown)." (PMID 29435159, 2018). "Of note is that this later lymphoma also has c-MYC overexpression (not shown)." (PMID 30687320, 2018). "A prior study of gene expression in lymphoma cells indicated a ∼25% overlap of genes induced by either BET inhibitors or HDAC inhibitors and suggested that the mechanism of synergy of BET plus HDAC inhibition in MYC-overexpressing cells is partly due to induction of HDAC-silenced genes." (PMID 30018745, 2018). "Moreover, emetine also induced the death of lymphoma cells without MYC rearrangement with a moderately higher IC50 value, and strongly inhibited the growth of various lymphoma cell lines with a GI50 ranging from 1.5 to 321 nM." (PMID 28055963, 2017).
lymphoma (continued). "Primary lymphoma cells without MYC rearrangement could also survive in co-culture with CAF for a longer time than in monoculture." (PMID 28055963, 2017). "Considering that emetine tended to be more effective in lymphoma with MYC rearrangement than in lymphoma without MYC rearrangement, emetine could be highly effective in tumor cells with increased glycolysis." (PMID 28055963, 2017). "In addition to the relationship between MYC and p27, there is a well-established inverse correlation between SKP2 and p27 the expression in many human tumors including thyroid, oral, breast, prostate, ovarian and lung cancer as well as lymphoma." (PMID 28665315, 2017). "The third group, “MYC-negative,” included MYC-negative lymphomas." (PMID 28379189, 2017). "Remarkably, the median lymphoma-free survival of Eμ-Myc;Rag-1-Cre;Mcl-1fl/+ mice (346 days) was far longer than in control Eμ-Myc (91 days) and Eμ-Myc;Rag-1-Cre mice (129 days, P**=0.003), clearly demonstrating the importance of MCL-1 in c-MYC-induced lymphomagenesis." (PMID 26962682, 2016). "The inverse correlation of BMAL1 versus MYC expression levels in human lymphomas and the absence of a positive correlation of MYC with circadian E-box genes support this hypothesis." (PMID 27339797, 2016). "Indeed, in a recent mouse model, it was shown that only the association of an EZH2 Y641 mutation and MYC overexpression, and not the EZH2 Y641 mutation alone, led to lymphoma development." (PMID 25762637, 2015). "Moreover, MYC was recently shown to interact with EZH2 and HDAC3 to repress miR-29 in lymphomas." (PMID 25644061, 2015). "In the near future, we hope to employ different MYC-driven lymphoma samples to test whether the transcriptional signatures that we observe here correlate with the particular MYC genetic lesion (translocated versus non-translocated)." (PMID 24466310, 2014). "Falling expression of ligand genes in 10-day Runx2/MYC thymus may be due to down-regulation or simple occlusion of non-lymphoid cells by nascent lymphoma cells, which is virtually complete at later stages." (PMID 24586197, 2014). "CYCLON knockdown did not alter MYC levels in Raji or other lymphoma lines tested." (PMID 23828858, 2013). "Since high-avidity TCRs for B cell differentiation antigens are not yet available, we have introduced chicken OVA into λ-hu-MYC lymphoma cells as a foreign antigen for which MHC class I- as well as class II-restricted TCR-transgenic mice and epitope-specific MHC class I-pentamers are available." (PMID 22479645, 2012). "To address whether BCL2A1 over-expression can promote development of leukemia/lymphoma, in the absence of a specific cooperating oncogene such as MYC, we used a murine bone marrow transplantation model." (PMID 23118966, 2012). "Thus, MYC lymphoma cells are capable of tumor-initiation and are not eliminated by rejection if more than 1×105 cells are transferred." (PMID 22479645, 2012). "In addition, we have demonstrated the GC origin of the BL tumors in our mouse model, whereas this was not the case for the lymphomas that developed in Igλ-MYC mice." (PMID 18578569, 2008). "However, the Thai Lymphoma Guideline 2022, mentions that in cases where the FISH technique cannot be used, IHC detects MYC and BCL2 expression, referred to as double expression (DE), which may correlate with a poorer prognosis than those without or with single expression." (PMID 39038016, 2024). "Notably, the absence of ARRDC3 markedly accelerated MYC-driven lymphoma development." (PMID 38097622, 2024).
lymphoma (continued). "Next, we generated cell lines from lymphomas from Eμ-MycT/+;Bcl-w+/+, Eμ-MycT/+;Bcl-w+/−, and Eμ-MycT/+;Bcl-w−/− mice (n = 5 each) to examine whether MYC-driven lymphomas that had developed in the absence of BCL-W would respond differently to anti-cancer agents." (PMID 37567974, 2023). "In addition, these cells had higher levels of the transcription factor Hes1 suggesting that NOTCH signalling might play a role in malignant transformation in GATA3-overexpressing cells, presumably via c-MYC, which is a direct target of NOTCH1 in T lymphoblastic leukaemia/lymphoma." (PMID 35681778, 2022). "Here we hypothesized that adaptive mechanisms to MYC-induced replicative and oxidative stress, consisting in DNA damage response (DDR) activation and BCL-2 overexpression, could represent the biologic basis of the poor prognosis and chemoresistance observed in MYC/BCL-2-positive lymphoma." (PMID 34304248, 2022). "In addition, 524 DMRs might be putative targets of Dnmt3b’s CA because they are hypermethylated in MYC;Dnmt3b+/+ lymphomas but not in MYC;Dnmt3bΔ/Δ or MYC;Dnmt3bCI/CI MTCLs that lack CA." (PMID 33450231, 2021). "In addition, 20–35% of DLBCL cases show co-expression of MYC and BCL2 by immunohistochemistry in the absence of chromosomal translocations, which represent “double expressor” lymphomas (DEL) also associated with poor clinical outcome, but are mainly of the ABC subtype." (PMID 33260693, 2020). "Previous studies in lymphoma, lung and liver cancers have also reported changes in lipid composition, signaling and metabolism with MYC amplification, suggesting that the relationship between MYC and lipids is not restricted to tumors developed from neural derived tissue." (PMID 29541417, 2018). "The crosstalk between MYC and p27 is also supported in vivo in p27 knockout mice, where lymphoma development was shown to co-occur with activation of MYC while such synergy could not be observed in p27 WT mice, thus strengthening the notion that p27 provides a negative feedback to MYC." (PMID 28665315, 2017). "A complex karyotype with c-MYC rearrangement, especially with chromosomal partners other than one of the immunoglobulin gene loci (chromosomes 14q, 2p and 22q) can indicate genomic evolution of the lymphoma cells into a high-grade B-cell lymphoma, NOS rather than development of Burkitt lymphoma." (PMID 28379189, 2017). "Notably, none of the modulatory effects induced by apoptotic lymphoma cells required macrophage IL-4Rα, indicating that the tumor-promoting effects of apoptotic λ-MYC cells and global IL-4Rα may be independent." (PMID 25702581, 2015). "Importantly, we compared the prognostic differences of double CNA with classic DHL and protein double expression (MYC and BCL2/BCL6 coexpression) lymphoma (DEL) and indicated the special value of double CNA which might be an important supplement to the DHL system." (PMID 26158410, 2015). "The inactivation of K-rasG12D but not MYC could induce complete tumor regression in lung adenocarcinomas; whereas in marked contrast, single K-rasG12D- or MYC-inactivation both succeeded in inducing sustained regression in lymphomas." (PMID 18461184, 2008). "Thus, MYC and K-rasG12D cooperate to induce lymphoma but not lung adenocarcinoma." (PMID 18461184, 2008). "The results showed negative MYC and BCL-2 gene rearrangements, thereby ruling out double-hit lymphoma." (PMID 41445799, 2025). "The lymphoma exhibited a Burkitt lymphoma-like immunophenotype and a high proliferation rate of ~90%, but FISH was negative for MYC rearrangement." (PMID 41374977, 2025). "No MYC or BCL2 FISH discrepancies were found in any pair and, therefore, assessment for “double-hit” lymphoma would not have changed." (PMID 38903717, 2024).